CYP4A11 (cytochrome P450 family 4 subfamily A member 11)
Diseases named in the same sentence as CYP4A11 in open-access papers (continued):
Sharing a sentence is not in itself a finding about the gene and the disease.
lung carcinoma (2 papers, 2015 to 2021). "Multivariate Cox regression analysis of gender, age, stage, cancer type, GAPDHS, ACSBG1, and CYP4A11 found that older (>60 years) age, highly expressed GAPDHS, low expressed ACSBG1, and low expressed CYP4A11 were high-risk factors for lung cancer prognosis." (PMID 34970420, 2021). "Three survival-related differentially expressed MMRGs were found, including GAPDHS, ACSBG1, and CYP4A11, in lung cancer." (PMID 34970420, 2021). "The advanced age, high expression of GAPDHS, low expressions of ACSBG1 and CYP4A11, and ACOX3 mutation were biomarkers of poor prognosis in lung cancers." (PMID 34970420, 2021). "Our study found the significantly high expression of GAPDHS, low expression of ACSBG1, and low expression of CYP4A11 in lung cancer tissues predicted poor prognosis for survival, whatever with single-factor and multifactor survival analytical strategies." (PMID 34970420, 2021). "(iii) The survival prognosis of lung cancer patients was better in the high expression group than low expression group of CYP4A11 (p < 0.05)." (PMID 34970420, 2021). "High expression of GAPDHS, low expression of ACSBG1, low expression of CYP4A11, mutated ACOX3, and old age predict a poor prognosis of lung cancer." (PMID 34970420, 2021). "In lung cancer tissue, high expression of GAPDHS, low expressions of ACSBG1, CYP4A11, mutated ACOX3, and old age predict a poor prognosis." (PMID 34970420, 2021). "The Oligo GRN hubgene CYP4A11 was shown to promote angiogenesis and metastasis in lung cancer and SLC38A3 (SNAT3) is a glutamine transporter and has been described as a marker for malignant glioma." (PMID 25971253, 2015). "Survival analysis of 43 differentially expressed MMRGs in lung cancer found that 3 differentially expressed MMRGs (GAPDHS, ACSBG1, and CYP4A11) had survival significance." (PMID 34970420, 2021).
metabolic dysfunction-associated steatotic liver disease (2 papers, 2023 to 2024). Metabolic dysfunction-associated steatotic liver disease (MASLD, formerly known as nonalcoholic fatty liver disease or NAFLD) is a type of liver disease that is not caused by alcohol. "Remarkably, CYP4A11 up-regulation has been associated with non-alcoholic fatty liver disease (NAFLD), since it increases the intracellular production of reactive oxygen species (ROS) and pro-inflammatory cytokines." (PMID 37505532, 2023). "During the progression of Metabolic Dysfunction-associated Steatotic Liver Disease (MASLD), activation of Phospholipase A2 (PLA2) releases arachidonic acid that CYP4A11 and CYP2E1 P450s metabolize to produce 20-hydroxyeicosatetraenoic acid (20-HETE) and 19-HETE, respectively." (PMID 40452921, 2024).
renal cell carcinoma (2 papers, 2020). "The goal of this study was to evaluate the clinicopathological role of CYP4A11 expression in renal cell carcinoma (RCC)." (PMID 32047554, 2020).
steatosis (2 papers, 2024). Increased lipid within the cytoplasm of cells. "The increased expression of the CYP2E1 and CYP4A11 genes in steatosis, with a down-regulation of the CYP2E1 P450 and elevated CYP4A11 in the progression of MASLD indicate the differential role of these genes." (PMID 40452921, 2024). "CYP4A11 mRNA levels significantly increased in steatosis and steatohepatitis." (PMID 39959811, 2024). "RNA seq database analysis of patients with MASLD revealed increased CYP4A11 and CYP4A22 mRNA in steatosis and MASH." (PMID 40452921, 2024). "Our data indicate that both CYP4A11, CYP4A22, and CYP4F2 mRNA levels increase in steatosis while both CYP4A11 and CYP4A22 increase in steatohepatitis." (PMID 39959811, 2024).
alcoholic cirrhosis (1 paper, 2023). "There was increased immunoreactivity of Cyp4a11/22 in patients with alcoholic cirrhosis compared to controls." (PMID 36624475, 2023). "By immunofluorescence/immunohistochemistry in human liver sections, there was increased immunoreactivity of Cyp4a11/22 in patients with alcoholic cirrhosis (n = 2) compared to healthy controls (n = 2)." (PMID 36624475, 2023). "By immunohistochemistry there was increased immunoreactivity of Cyp4a11/22 in liver sections from patients with alcoholic cirrhosis (n = 8) compared to heathy control livers (n = 8)." (PMID 36624475, 2023). "Human cholangiocytes express Cyp4a11/22, which is upregulated in the total liver from patients with alcoholic cirrhosis compared to healthy controls." (PMID 36624475, 2023).
alcoholic liver diseases (1 paper, 2021). A disorder caused by damage to the liver parenchyma due to alcohol consumption. "To determine if CYP4A is involved in ALD pathogenesis in humans, we detected the mRNA expression of CYP4A11 (homolog of murine Cyp4a14) and CYP4A22 (homolog of murine Cyp4a10) in the liver of patients with alcoholic liver disease." (PMID 34423788, 2021).
clear-cell renal cell carcinoma (1 paper, 2021). "CYP4A11 is one member of cytochrome P4504 (CYP4) family involved in the metabolisms of fatty acids, which is downregulated in liver cancer tissues and in clear-cell renal cell carcinoma tumor tissues." (PMID 34970420, 2021).
coronary atherosclerosis (1 paper, 2018). Atherosclerosis of the coronary vasculature. "The study of White with coworkers provided evidence that polymorphism in the CYP4A11 gene is related with disorders underlying coronary atherosclerosis, and this relationship is also sex specific." (PMID 29484037, 2018).
glioma (1 paper, 2019). A benign or malignant brain and spinal cord tumor that arises from glial cells (astrocytes, oligodendrocytes, ependymal cells). "First, we have provided direct evidence that ISL is a potent COX-2, mPGES-1 and CYP4A11 inhibitor, and thereby blocks angiogenesis and induces vascular normalization in glioma through downregulation of FGF-2, TGF-β and VEGF." (PMID 31438982, 2019). "Given that glioma cells in culture show negligible 20-HETE synthesis, CYP4A was overexpressed by transfection with CYP4A11 lentiviral activation particle in the C6 and U87 cells." (PMID 31438982, 2019).
hemorrhagic stroke (1 paper, 2019). A stroke caused by a bleed on the brain. "The production of 20-HETE is elevated after the onset of both ischemic and hemorrhagic strokes; on the other hand, subjects with genetic variants in CYP4F2 and CYP4A11 that reduce 20-HETE production are more susceptible to stroke." (PMID 31514409, 2019).
Hepatic steatosis (1 paper, 2016). Steatosis is a term used to denote lipid accumulation within hepatocytes. "Amongst the top Toxicity functions was hepatic steatosis (p = 6.99x10-4) with associated genes including Acaca, Cbs, Ccnd1, Cyp4a11, Ddc, Gstp1, Insig2, Por and Rorc." (PMID 26968002, 2016).
hypertensive nephropathy (1 paper, 2020). Kidney damage that results from chronically elevated blood pressure; complications include glomerular damage resulting in proteinuria and hematuria. "We observed decreased expression of CYP4F22 mRNA in the decliner group; downregulation of CYP4A11 mRNA, another CYP4 isoform involved in 20-HETE generation, was already described in a gene expression profile of renal biopsies from patients with hypertensive nephropathy." (PMID 32425885, 2020).
hypospadias (1 paper, 2020). Hypospadias is the displacement of the urethral meatus on the ventrum of the penis. "We identified a significant causal effect of methylation at cg04714159 on hypospadias, as well as potential causal effects of multiple members of the cytochrome P450 family of enzymes in this region (CYP4A11, CYP4A22, CYP4B1, CYP4X1, CYP4Z2P)." (PMID 32728162, 2020).
liver cancer (1 paper, 2021). An epithelial or non-epithelial malignant neoplasm that arises from the liver. "CYP4 enzyme participates in maintenance of the normal range of fatty acids and fatty acid-derived bioactive molecules, such as CYP4A11 is downregulated in liver cancer tissues." (PMID 34970420, 2021).
liver cirrhosis (1 paper, 2024). "Unlike CYP4A11 mRNA and P4504A11 protein that dramatically decrease in liver cirrhosis patients, CYP4A22 mRNA and P4504A22 protein levels increase." (PMID 39959811, 2024).
Stroke (1 paper, 2019). Sudden impairment of blood flow to a part of the brain due to occlusion or rupture of an artery to the brain. "The available evidence seems to suggest that reduced 20-HETE levels may predispose to the development of stroke, although alterations in 20-HETE production associated with many of the human CYP4F2 and CYP4A11 SNPs have not been defined." (PMID 31514409, 2019).
tumor (10 papers, 2013 to 2026). "In GSE14520 dataset, we identified the fact that low expressions of four CYPs including CYP2A6, CYP2C8, CYP2E1, and CYP4A11 in tumor tissues were significantly associated with worse OS in HCC patients (log ranks P = 0.01, 0.006, 0.024, and 0.007, respectively)." (PMID 30148168, 2018). "Seven CYP450 genes including CYP1A2, CYP2A6, CYP2C8, CYP2C9, CYP2E1, CYP3A4, and CYP4A11 were downregulated in tumor tissues, which were validated in both GSE14520 and GSE36376." (PMID 30148168, 2018). "In our study, we found that several CYPs including CYP1A2, CYP2A6, CYP2C8, CYP2C9, CYP2E1, CYP3A4, and CYP4A11 were all downregulated in tumor tissues in HCC patients." (PMID 30148168, 2018). "In vivo, CYP4A11 transfection significantly increased tumor weight, microvessel density, and lung metastasis, whereas HET0016 or 6,15,20-HEDE administration decreased tumor volume, microvessel density, and spontaneous pulmonary metastasis occurrences." (PMID 28230738, 2017). "However, the expressions of ACSBG1 and CYP4A11 in four tumor stages (stages I, II, III, and IV) were statistically significant difference, respectively (p < 0.05)." (PMID 34970420, 2021). "Furthermore, the identified hub genes of the individual GRNs, e.g., HID1/DMC1 (tumor development), RNF17/TDRD4 (cancer antigen) and CYP4A11 (angiogenesis/ metastasis) are known cancer associated markers." (PMID 25971253, 2015). "While down-regulation of genes such as CYP4A11, PLA2G4A, PLA2G3, LTC4S, CYP27A1, HMGCS2 and PDPK1 reduced patient overall survival time in most tumor types." (PMID 31074374, 2019). "Tumor transcriptome deconvolution identifies significant down-regulation of epithelial cell polarity, including PATJ (1p31), and fatty acid metabolism, including CYP4A11 (1p33), in cancer cells of tumors that develop metastatic progression." (PMID 41741714, 2026).
cancer (6 papers, 2015 to 2026). A tumor composed of atypical neoplastic, often pleomorphic cells that invade other tissues. "We identified hub genes such as HID1 (RNAseq) RNF17 (TDRD4) (Bead), CYP4A11 (Oligo) for the individual GRNs which show in the literature strong evidence for cancer related diagnostic and prognostic properties." (PMID 25971253, 2015). "Conversely, CYP2C8 and CYP4A11 showed high expression and good prognosis, suggesting a potential protective role against cancer pathogenicity." (PMID 32851080, 2020). "The different expressions of CYP4A11 between ccRCC and non-ccRCC can be correlated with different metabolism of each cancer type." (PMID 32047554, 2020).
cardiovascular diseases (4 papers, 2013 to 2022). "Genetic variants of CYP4F2 and CYP4A11 genes are reportedly associated with cardiovascular diseases such as hypertension." (PMID 31480463, 2019). "CYP4A11 is known to be highly polymorphic, expanding the possibilities for studying the mechanism of action of this gene, especially as a risk factor for cardiovascular diseases." (PMID 24278241, 2013). "Genetic variants of CYP4A11, 4F2 genes are associated with cardiovascular diseases." (PMID 31480463, 2019). "Several researches have displayed that genetic polymorphisms in CYP4 family genes such as CYP4A11 and CYP4F2 are related to the susceptibility to cardiovascular diseases." (PMID 36437455, 2022). "Another SNP rs3890011 in intron of CYP4A11 was also a subject of investigations in cardiovascular disorders in various populations of the world." (PMID 29484037, 2018). "CYP4A11 and CYP4F2 are highly polymorphic genes which became attractive candidates for association studies of cardiovascular diseases." (PMID 29484037, 2018). "Various studies have revealed that single nucleotide polymorphisms (SNPs) in CYP4A11 and CYP4F2 have an impact on expression or catalytic activity of these enzymes, thereby contributing to the molecular basis of cardiovascular disorders including CAD." (PMID 29484037, 2018).
CYP4A11 also shares sentences with these, for which no sentence is quoted: diabetic kidney disease (2 papers); essential hypertension (2); injury (2); alcoholic fatty liver disease (1); cerebrovascular diseases (1); endothelial dysfunction (1); infection (1); Insulin resistance (1); liver fibrosis (1); lung adenocarcinoma (1); lung squamous cell carcinomas (1); malignant glioma (1); Obesity (1); papillary renal cell carcinoma (1); portal hypertension (1); resistant hypertension (1).